GHR (growth hormone receptor)
Diseases named in the same sentence as GHR in open-access papers (continued):
Sharing a sentence is not in itself a finding about the gene and the disease.
Laron syndrome (continued). "Similarly, mutations in growth hormone receptors (GHR) can lead to Laron syndrome (LS), one of the several disorders that are collectively called growth hormone insensitivity syndrome (GHI)." (PMID 32935225, 2020). "Moreover, patients with Laron syndrome caused by the GHR mutations have significant trunk obesity and body composition change." (PMID 33519913, 2020). "Until now, more than 90 GHR mutations relevant to human short stature (Laron syndrome and idiopathic short stature), including deletions, missense, nonsense, frameshift, and splice site mutations, and four GHR defects associated with chicken dwarfism, have been described." (PMID 29748515, 2018). "We further evaluated the expression of GHR at the transcription and translation levels, as determining whether GHR mutations result in protein dysfunction and induce Laron syndrome phenotypes is important." (PMID 29482569, 2018). "In humans with Laron syndrome, a mutated GH receptor (GHR) affects mammary gland development." (PMID 28451590, 2017). "Furthermore, the congenital deficiency of IGF-I or IGF-IR are features of the Laron syndrome, which also includes growth hormone receptor (GHR) deficiency and/or the alteration of molecules of the GH and IGF-I signaling pathways." (PMID 26941597, 2016). "GH receptor (GHR) mutations were shown to cause Laron syndrome with extreme growth failure." (PMID 26902202, 2016). "Importantly, similar results have been reported in growth hormone receptor-deficient Laron syndrome (LS) patients." (PMID 25902704, 2015). "Primary growth hormone resistance or growth hormone insensitivity syndrome, also known as Laron syndrome, is a hereditary disease caused by deletions or different types of mutations in the growth hormone receptor gene or by post-receptor defects." (PMID 21745362, 2011). "Mutations in GHR cause Laron syndrome, a rare disease (ORPHA:633) characterized by marked short stature, low serum IGF-1 levels and auditory defects like late onset SNHL, auditory hypersensitivity and lack of acoustic stapedial reflexes, which may be prevented by IGF-1 treatment." (PMID 34680948, 2021). "In addition GHR/IGF-I deficiency is also among the few phenotypes that is well characterized in humans (patients with Laron syndrome) with very few side effects in adults, even considering the extreme level of GH receptor deficiency and the resulting >80% reduction in circulating IGF-I." (PMID 25902704, 2015). "From a therapeutic perspective, recombinant IGF-I (rhIGF-I) is the primary treatment for patients with classical GHI due to GHR defects and is approved for use in Laron syndrome." (PMID 40723048, 2025). "As pigs closely resemble human anatomy, physiology and metabolism in particular, we studied the metabolic alterations due to GH insensitivity in a large animal model for Laron syndrome (the GHR-KO pig) in an age-dependent manner." (PMID 41125144, 2025). "GH insensitivity due to growth hormone receptor (GHR) deficiency (GHRD, human Laron syndrome, LS) is characterized by postnatal growth retardation and alterations in body composition." (PMID 41125144, 2025). "Laron syndrome, first described in 1966, was the first recognized cause of GHI, most commonly caused by homozygous mutations in the GHR gene, which encodes the GHR." (PMID 40868191, 2025). "The GHR-/- mice, which model individuals with Laron Syndrome, exhibit improved cognition, resistance to diabetes, and reduced neoplasia." (PMID 38831184, 2024). "Our focus centers on the growth hormone receptor (GHR) gene, the disruption of which results in Laron syndrome, characterized by reduced stature." (PMID 38559814, 2024). "We were able to show that GH insensitivity impedes β-cell maturation and function and that the GHR-KO pig resembles the phenotype of human Laron syndrome (LS) patients who display increased insulin sensitivity despite obesity." (PMID 38960990, 2024).
Laron syndrome (continued). "Laron syndrome is the best characterized form of SPIGFD, caused by a defect in the GH receptor (GHR) gene." (PMID 37805563, 2023). "The only treatment tested for growth hormone receptor (GHR) defective Laron Syndrome (LS) is injections of recombinant insulin-like-growth factor 1 (rhIGF1)." (PMID 35105948, 2022). "Laron syndrome (LS), the best characterized entity under the spectrum of the congenital IGF1 deficiencies, results from mutation of the GH receptor (GHR) gene, leading to dwarfism, obesity and other defects." (PMID 34769292, 2021). "Compared to the healthy human population, HMW adiponectin levels are significantly increased in patients with molecular defects in GHR gene (Laron syndrome)." (PMID 33755309, 2021). "Similar to Laron syndrome phenotype, global GHR knockout mice (GHR–/–) showed GH tolerant, obese, highly sensitive to insulin, enhanced glucose assimilation, and extended longevity." (PMID 33519913, 2020). "Steatosis was also observed in a proportion of patients with growth hormone receptor (GHR) deficiency (Laron syndrome; OMIM reference 262500) and in mice with a liver-specific deletion of the GHR." (PMID 32277923, 2020). "Laron syndrome, or primary GH insensitivity (OMIM#262500), is an autosomal recessive hereditary disease caused by molecular defect of the GHR gene, leading to GH resistance and dwarfism." (PMID 33182502, 2020). "GHR-KO pigs resemble the clinical hallmarks of human Laron syndrome and can be maintained under standardized conditions, thus minimizing variance induced by confounding factors." (PMID 32277923, 2020). "Several studies have confirmed that GHR knock-out resulted in a delay in puberty onset, and this echoes the delayed puberty that is observed in human disorders such as Laron dwarfism where GHR is dysfunctional." (PMID 31781044, 2019). "GHR -/- animal models have the pattern of Laron Syndrome, AOiGHD would be equivalent to acquired isolated GHD in adults and the newer GH -/- animal model would simulate what happens in isolated GHD syndrome." (PMID 31939483, 2019). "We employed CRISPR/Cas9 technology to generate GHR knockout (GHR-KO) pigs as a large animal model for Laron syndrome (LS)." (PMID 29678421, 2018). "Taken together, the Laron pig is an improved model for studying the effects of GHR defects on growth and metabolism observed in Laron syndrome and for assessing the efficacy of Laron syndrome treatments." (PMID 29482569, 2018). "In summary, GHR-KO pigs resemble important aspects of the pathophysiology of human Laron syndrome and are thus an interesting model for mechanistic studies and treatment trials." (PMID 29678421, 2018). "Defects in the GHR protein, resulting from abnormalities of the GHR gene, have been shown to result in the clinical phenotypes of classical Growth Hormone Insensitivity or Laron Syndrome." (PMID 29025428, 2017). "Here we used ZFNs to produce a human Laron syndrome disease model in miniature pigs by knocking out the GHR gene." (PMID 26511035, 2015). "In summary, we generated a miniature pig disease model for human Laron syndrome by knocking out the GHR gene." (PMID 26511035, 2015). "The murine equivalents to human Laron syndrome are GH receptor/binding protein homozygous knockout mice (GHR/BP-/-)." (PMID 19412415, 2007). "•GHR-KO pigs show transient juvenile hypoglycemia, resembling human Laron syndrome." (PMID 41125144, 2025). "Similarly, mice with a GHR deletion (Ghr−/−), which models Laron syndrome (characterized by low levels of IGF-1), exhibit increased longevity and metabolic benefits." (PMID 40260058, 2025). "Laron syndrome (LS) is a rare genetic disorder characterized by low levels of insulin-like growth factor 1 (IGF1) and high levels of growth hormone (GH) due to mutations in the growth hormone receptor gene (GHR)." (PMID 37189345, 2023).
Laron syndrome (continued). "Laron syndrome (LS) is a rare inherited disorder characterized by low circulating insulin-like growth factor 1 (IGF1) and high circulating growth hormone (GH) due to mutations in the growth hormone receptor gene (GHR)." (PMID 37189345, 2023). "An enlightening fact is that patients with Laron syndrome who have growth hormone receptor (GHR) mutations have an IGF-1 deficiency, and if they are not treated with IGF-1 recombinant, they never develop acne." (PMID 35889022, 2022). "The disruption of GHR also cause Laron syndrome (microcephalic syndrome) which not only affects the brain but also total somatic dwarfism." (PMID 33891593, 2021). "Provided that suppression of GHR signaling in GHR-/- mice leads to major extension of longevity, could the same be concluded about patients with Laron syndrome?" (PMID 30542372, 2018). "For example, GH resistance of “Laron dwarf” GHR-/- mice is due to deletion of most of the fourth exon and part of the fourth intron of the Ghr gene, while Laron syndrome in different human cohorts is due to various deletions, splice variants, nonsense, missense, or frameshift mutations." (PMID 30542372, 2018). "Laron syndrome was confirmed after the molecular analysis of the GH receptor (GHR) gene." (PMID 29850346, 2018). "Finally, humans with Laron syndrome (LS) and GHR gene disrupted (GHR-/- or aGHRKO) mice, which are fully or partially unable to respond to GH, provide an opportunity to evaluate GH insensitivity." (PMID 28933734, 2017). "In the hypothesis of a case of Laron Syndrome, we performed the direct sequencing of the complete coding sequence of GHR gene that revealed the presence of two heterozygous variation." (PMID 29025428, 2017). "In the hypothesis of Laron Syndrome, we decided to perform a molecular analysis of Growth Hormone Receptor (GHR) gene." (PMID 29025428, 2017). "The pigs obtained with one disrupted GHR allele did not exhibit remarkable Laron syndrome phenotypes." (PMID 26511035, 2015). "Interestingly, a defect in the GHR, as seen in Laron syndrome, protects from cancer." (PMID 39459020, 2024). "Similarly, GHR‐KO mouse model of the Laron syndrome showed increased levels of HMW adiponectin." (PMID 33755309, 2021). "Growth hormone receptor (GHR) knock-out mice (GHR-KO), also called Laron dwarf mice, correspond to one form of human dwarfism known as Laron syndrome." (PMID 24063422, 2013). "Another classic genetic model of increased lifespan in mammals is the growth hormone receptor (GHR) knock-out mouse, as well as its corresponding genetic defect in humans (Laron syndrome), which is characterized by extreme insulin sensitivity and protection to cancer." (PMID 30926763, 2019). "Taken together, the available data indicate that GHR dysfunction in Laron syndrome patients protects them from cancer and diabetes, but has no significant impact on longevity." (PMID 30542372, 2018). "Three types of F0 heterozygous pigs (GHR+/4bp, GHR+/2bp, GHR+/3bp) were obtained and in which no significant phenotypes of Laron syndrome were observed." (PMID 26511035, 2015). "Epidemiological evidence demonstrated that patients affected by Laron syndrome, a disease characterized by congenital IGF1 deficiency, due to the occurrence of homozygous mutations in the growth hormone receptor (GHR) or GH-induced intracellular signaling, do not develop cancer." (PMID 38892104, 2024). "Furthermore, no incidence of breast cancer has been observed in patients with Laron syndrome where the GHR is non-functional." (PMID 34206988, 2021). "Indeed, patients with Laron syndrome, which is a congenital IGF-1 deficiency caused by a growth hormone receptor mutation, never present with acne unless they are treated." (PMID 26413187, 2014).
acromegaly (66 papers, 2011 to 2025). Acromegaly is an acquired disorder related to excessive production of growth hormone (GH) and characterized by progressive somatic disfigurement (mainly involving the face and extremities) and systemic manifestations. "Polymorphisms in GHR, such as d3-GHR, has been studied in acromegaly but correlation with clinical features or therapeutic outcomes has not been consistent." (PMID 36545335, 2022). "Dysregulation of GHR signaling is associated with various diseases and chronic diseases, such as acromegaly, cancer, aging, metabolic diseases, fibrosis, inflammation, and autoimmunity." (PMID 36120336, 2022). "Dysregulation of GHR signaling is associated with various diseases and chronic conditions such as acromegaly, cancer, aging, metabolic disease, fibroses, inflammation and autoimmunity." (PMID 33312162, 2020). "In adults, hypersecretion of GH causes acromegaly, and strategies that block the release of GH or that inhibit GH receptor (GHR) activation are the primary forms of medical therapy for this disease." (PMID 30775002, 2019). "The exon 3 deleted GHR isoform (d3-GHR) is associated with better response to PEG therapy in acromegaly." (PMID 27267119, 2016). "Our study proved for the first time that the GHR polymorphisms may orient the choice of second-line medical therapies in acromegaly, considering the prevention of acromegaly-related comorbidities, such as bone health." (PMID 39280003, 2024). "This study aims to deepen our knowledge of the genetic and cellular mechanisms involved in bone metabolism in acromegaly, by examining the potential predictive value of the GH receptor (GHR) isoforms on the occurrence of i-VFs." (PMID 39280003, 2024). "Although treatment of acromegaly with the GH receptor (GHR) antagonist pegvisomant achieves a high rate of long-term biochemical control and can improve acromegaly comorbidities, little is known about its effects on the bone disease of acromegaly." (PMID 38715589, 2024). "Overall, although deficits remained in pegvisomant-treated patients, our results suggest that long-term GHR blockade has a similar impact on the bone disease of acromegaly as other forms of acromegaly treatment." (PMID 38715589, 2024). "The distribution of the GHR genotypes (fl/fl, fl/d3, and d3/d3) was examined in numerous studies involving acromegaly patients, and in most studies, roughly half of acromegaly patients carried at least one d3 allele." (PMID 37762211, 2023). "GHR expression is observed in normal somatotroph cells and to a lesser degree in somatotroph adenomas." (PMID 36545335, 2022). "GHR is the target of the peripheral GHR antagonist pegvisomant, which is highly effective in treating acromegaly both as monotherapy and in combination with SRL." (PMID 36545335, 2022). "Of note is that pegvisomant is a small peptide that blocks the binding and interactions between GHR and GH and is currently used to treat acromegaly patients who suffer increased GH secretion and hyperactivity of GHR." (PMID 36276070, 2022). "The translation of these results to the clinic is feasible, given the availability of FDA-approved GHR antagonist Pegvisomant, which is currently approved for acromegaly and known to successfully normalize serum IGF1 in >90% of the patients." (PMID 35865483, 2022). "When SSAs treatment alone cannot achieve biochemical control of acromegaly, the SSAs can be replaced or combined with the growth hormone receptor antagonist pegvisomant (PEG)." (PMID 33869029, 2021). "In summary, ATL1103 lowers IGF-I in acromegaly with biochemical changes consistent with downregulation of the GHR." (PMID 29789410, 2018). "In summary, the bGH and the GHR−/− mice have opposing genotypes and phenotypes and serve as commonly utilized animal models of the human diseases acromegaly and LS." (PMID 28670222, 2017).
acromegaly (continued). "In parallel to human models of GH over or under expression, the phenotype of the GHR−/− mouse is very similar to patients with Laron syndrome (LS), while the bGH mouse phenotype is similar to patients with gigantism and acromegaly." (PMID 28670222, 2017). "Three drug classes are currently available for acromegaly therapy: somatostatin analogues (SA), dopamine agonists (DA) and GH receptor (GHR) antagonists." (PMID 27737325, 2016). "Pegvisomant (PEGv) is a growth hormone receptor antagonist approved for the treatment of acromegaly; one of its documented adverse effects is reversible elevation of hepatic enzymes." (PMID 26977326, 2016). "The d3GHR deletion is the most investigated polymorphism of GHR in both healthy subjects and patients with GHD or other diseases such as acromegaly or type 2 diabetes." (PMID 24498035, 2014). "Alternative medical therapies, such as somatostatin analogs or growth hormone receptor antagonists, may be considered in the management of acromegaly while avoiding dopamine agonist–related side effects." (PMID 41221015, 2025). "Growth hormone excess usually responds well to somatostatin analogs such as octreotide and lanreotide or growth hormone receptor antagonists (pegvisomant), whether used individually or combined." (PMID 39618732, 2024). "GH receptor (GHR) polymorphisms, and particularly d3-GHR have been involved in different sensitivity to GH and to the different necessity of pegvisomant dosage to get hormonal control during acromegaly treatment." (PMID 33796079, 2021). "Growth hormone receptor antagonists have been another addition to the treatment of acromegaly." (PMID 24062868, 2013). "In cases in which cabergoline alone is not sufficient to stop growth hormone excess, the somatostatin analogue octreotide or the growth hormone receptor antagonist pegvisomant may be additionally beneficial for the treatment of acromegaly." (PMID 22273876, 2012). "ASOs targeting the growth hormone receptor (GHR) may be a novel therapy for acromegaly." (PMID 39944202, 2025). "One reference was about mortality and cancer incidence in acromegaly, one focused on long-term mortality after transsphenoidal surgery and adjunctive therapy for acromegaly, and one was about the treatment of acromegaly with the growth hormone-receptor antagonist pegvisomant." (PMID 37476831, 2023). "Pegvisomant (PEGV) is a brand-new GHR antagonist, which improves symptoms and maintains IGF-1 balance in acromegaly patients over the course of up to 12 weeks of treatment." (PMID 37762211, 2023). "Current pharmacological options for patients with acromegaly include somatostatin receptor ligands (SRL), growth hormone receptor agonist, and dopamine agonists (DA)." (PMID 36545335, 2022). "A novel drug in development, Cimdelirsen (IONIS-GHR-LRx; ISIS 766720), which is an antisense molecule that acts by reducing GHR synthesis in the liver, has also shown promise in treating acromegaly." (PMID 36545335, 2022). "For example, pegvisomant, a growth hormone receptor antagonist, is used for normalizing IGF-1 levels in acromegaly and teprotumumab, which antagonizes IGF-1R, is used to treat thyroid eye disease." (PMID 32492897, 2020). "The data presented provide the ‘proof of concept’ that in patients with acromegaly, an ASO targeting the GHR can lower serum IGF-I and raise the prospect of a new and entirely novel therapy for acromegaly." (PMID 29789410, 2018). "Because PEGV is a competitive blocker of the GH receptor (GHR), pharmacology dictates that in principle it should be possible to control IGF-I levels in all patients with acromegaly, provided that the appropriate PEGV dose is used." (PMID 26661938, 2016).